STAT3 (signal transducer and activator of transcription 3)
Diseases named in the same sentence as STAT3 in open-access papers (continued):
Sharing a sentence is not in itself a finding about the gene and the disease.
asthma (continued). "Additionally, an asthma mouse model was established to quantify the levels of TGF-β1 in serum using enzyme-linked immunosorbent assay (ELISA), and evaluate the expression levels of TGF-β1, total-STAT3, p-STAT3, and CTGF proteins in lung tissue through Western blot analysis." (PMID 38708080, 2024). "The protein expression levels of TGF-β1, p-STAT3, and CTGF in the lung tissue of asthma mice were significantly elevated compared to those in the control group (p < 0.05), as demonstrated by Western blot analysis." (PMID 38708080, 2024). "The complex IL-6/IL6R triggers a cascade that activates STAT3 and CEBP transcription factors, both involved in airway inflammation and asthma." (PMID 36979655, 2023). "This study shows that asthma can regulate the HIF-1 signaling pathway, promoting the expression of IL6, Stat3, and HIF-1α protein and mRNAs, so as to promote sperm apoptosis and ultimately causing male infertility." (PMID 35620222, 2022). "The LPS stimulation of human neutrophils from severe asthma and COPD patients increased the phosphorylation of JAK2 and STAT3 as well as the phosphorylation of ERK1/2 and P38." (PMID 35332239, 2022). "Methyl rosmarinate (degree, 8; betweenness centrality, 0.02733; closeness centrality, 0.4715) also shared the same targets (STAT3, PIK3CB, MAPK1, ESR1, SYK, and EGFR) and identical asthma-related signaling pathways with caffeic acid." (PMID 35572723, 2022). "In this work we confirmed that LPS phosphorylates JAK2/STAT3, ERK1/2 and P38 in neutrophils from severe asthma and COPD patients which were attenuated by LAS194046, showing synergic inhibitory effects when combined with fluticasone propionate." (PMID 35332239, 2022). "In the pathogenesis of asthma, with the activation of IL6 and Stat3 proteins, HIF-1α protein expression increases under the IL-6/Stat3/HIF-1α signaling pathway, which then promotes the apoptosis of spermatogenic cells, affecting sperm quality." (PMID 35620222, 2022). "Asthma can regulate the HIF-1 signaling pathway, promoting the expression of IL6, Stat3, and HIF-1α protein and mRNAs, so as to promote sperm apoptosis and ultimately causing male infertility." (PMID 35620222, 2022). "The role of STAT3 and SOCS3 in asthma has been discussed in relation to the T2-mediated allergic response." (PMID 34760922, 2021). "There is still lack of study in effects of ozone exposure on SOCS3, and few scholars have focused on the role of STAT3 and SOCS3 in the mechanism of action of T2-low asthma and corticosteroid resistance." (PMID 34760922, 2021). "Our study demonstrated that rhynchophylline can alleviate asthma through suppressing autophagy in asthma, and that JAK2/STAT3 signal was involved in this effect of rhynchophylline." (PMID 33413331, 2021). "Our analyses in the human lung tissue of the expression of STAT3 and SOCS3 further convinced us that STAT3 and SOCS3 are involved in asthma." (PMID 34760922, 2021). "We conclude that AG inhibits the inflammatory response of asthma in OVA-stimulated mice by blocking the activation of Th17-regulated cytokines and the JAK1/STAT3 signaling pathway." (PMID 34194525, 2021). "The correlation between the expression of STAT3 or SOCS3 and airway inflammation indicated that STAT3 and SOCS3 are involved in asthma." (PMID 34760922, 2021). "Specifically, epithelial STAT3 was identified as a critical regulator of allergen-induced inflammation and AHR in a murine model of asthma." (PMID 31931796, 2020). "The combined interaction scores resulted in higher interactions for the genes STAT3, AGO2, COL1A1, CLCN6, and KSR for moderate asthma and JAK2, INSR, ERBB2, NR3C1, and PTK6 for severe asthma." (PMID 32512817, 2020). "STAT3 is a known effector of PM; IRF4 is also known for its function in Asthma by activating Th17 through regulation of chromatin accessibility but not for the role in response to PM exposure." (PMID 32448264, 2020).
asthma (continued). "IL-6R, a prominent ADAM17 substrate linking the axis to STAT3 in trans-signaling, is a modifier of COPD as well as asthma." (PMID 29540993, 2018). "Using quantitative real-time polymerase chain reactions (qRT-PCR), the transcript levels of STAT3 and STAT5a were evaluated in peripheral blood mononuclear lymphocytes (PBML) isolated from 13 patients with SRA, 14 with mild asthma, and 30 healthy volunteers." (PMID 28638418, 2017). "Previous reports have demonstrated the central role of Stat3 signaling in TSLP-regulated inflammation and airway remodeling in asthma." (PMID 24167583, 2013). "In summary, IL-13 may promote ferroptosis and inflammation by activating JAK2/STAT3 and EPAS1, leading to 16HBE cell damage and potentially contributing to asthma progression." (PMID 40165005, 2025). "There is evidence that treatment of allergic asthmatics with inhaled steroids was able to reverse the high levels of IL-5, IL-13 and IL-9 produced by ILC2s via STAT3, STAT5, STAT6, JAK3 and MEK signaling pathways, which was accompanied by better asthma control." (PMID 39452061, 2024). "Ciglitazone has been shown to be dependent on NF-κB- and STAT3-related pathways, thus, the PPAR-γ agonist may have therapeutic potential for the treatment of airway remodelling in asthma." (PMID 37259630, 2023). "A total of 129 overlapping targets between the PEF and asthma were obtained by jvenn online tools, among which five targets might play important roles: MAPK14, JUN, STAT3, MAPK3, and MAPK1." (PMID 36172200, 2022). "Among these components, caffeic acid might be recognized as an essential active compound in H. cuspidatus containing multiple targets, including STAT3, EGFR, and PIK3CA, that contributed to treating asthma." (PMID 35572723, 2022). "Polymorphisms of IL-10, IL-10R, and STAT3, a Janus kinase (JAK)–signal transducer and activator of transcription, activated downstream of IL-10R were found to be associated to asthma and higher levels of IgE, without interfering with IL-10 levels." (PMID 34924814, 2021). "Our subsequent molecular docking showed that each bioactive compounds (quercetin, wogonin, luteolin, naringenin, and kaempferol) of MGMD has favorable binding abilities with STAT3, PTGS2, JUN, VEGFA, EGFR, and ALOX5, further arguing the potential molecular mechanism of action of MGMD in asthma." (PMID 33968984, 2021). "STAT3 and SOCS3 appeared to be involved in asthma pathogenesis in mouse models and asthma patients." (PMID 34760922, 2021). "The STAT3-positive area increased in the lung tissue of asthma patients compared with that in HCs, whereas SOCS3 expression decreased in the lung tissue of asthma patients." (PMID 34760922, 2021). "The anti-inflammatory effects of CTS against OVA-induced airway remodeling may be through inhibiting STAT3, which further suppresses TWEAK and TGF-β1 signaling cross talk in asthma." (PMID 31780948, 2019). "Our study revealed that STAT3 gene expression was not significantly different between the three groups of healthy controls, asthma and severe asthma." (PMID 28638418, 2017). "Our study, therefore, aimed to investigate STAT3 and STAT5 gene expression in asthma and SRA." (PMID 28638418, 2017). "There is some evidence supporting the involvement STAT3 and STAT5 in the development of asthma." (PMID 28638418, 2017). "Likewise, the inhibition of STAT3 and STAT5 ameliorated experimental asthma by modulating lung CD11c(+) dendritic cells phenotype and function." (PMID 23737822, 2013). "Particularly, epithelial STAT3 was identified as a critical regulator of allergen-induced inflammation and AHR in a murine model of asthma, IL-17A-induced STAT3 activation led to CCL11/eotaxin-1 production in HASM, and PDGF-induced STAT3 mediated the proliferation in HASM cells." (PMID 24499258, 2013). "In addition, the Stat3-targeted inhibitor, WP1066, was evaluated in an asthma mouse model to determine if inhibiting cellular senescence influences airway remodeling in asthma." (PMID 24167583, 2013).
asthma (continued). "Additionally, GAL reduced JAK/STAT3 expression in acute kidney injury (AKI) model through modulation of NF-κB (p65) and IL-6/JAK2/STAT3/SOCS3 signals via α7nAChR and in experimental asthma model, α7nAChR exerted promising effects by inhibiting NF-κB/STAT3/SOCS3 signaling." (PMID 37429998, 2024). "STAT genes are present in several homologues in the genome, and in humans, defects, for example in STAT3 gene, have been connected with hyper‐IgE syndrome and atopic dermatitis and NPSR1 has been proposed to be involved in IgE‐mediated diseases in humans, such as allergic eczema and asthma." (PMID 33226152, 2021). "We found that STAT3 phosphorylation as well as the expression of IL-6 and IL-17A could not be reversed by Dex treatment, which indicates their involvement in corticosteroid resistance of OVA- and ozone-induced asthma." (PMID 34760922, 2021). "The IL-6/STAT3 pathway may contribute to corticosteroid insensitivity in OVA + ozone–induced neutrophilic airway inflammation through regulation of Th17 cells and could provide new targets for individual treatment of corticosteroid resistance in asthma." (PMID 34760922, 2021). "Thus, IL-6 and STAT3 may have important roles in an OVA- and ozone-induced corticosteroid-resistant asthma model." (PMID 34760922, 2021). "SOCS3 (a negative transcription factor) may interact with STAT3 and be involved in the corticosteroid insensitivity of the T2-low asthma model." (PMID 34760922, 2021). "For example, in severe asthma, the combined interaction scores for the STAT3, AGO2, COL1A1, CLCN6, and KSR1 genes yielded a higher interaction for the moderate asthma phenotype, and the JAK2, INSR, ERBB2, NR3C1, and PTK6 genes were more interactive for the severe asthma phenotype." (PMID 32512817, 2020). "Based on our results and previous studies, we hypothesize that, STAT3 may have some role in the metabolic pathways of asthma, however, it does not seem to be directly involved in the pathogenesis of asthma and SRA." (PMID 28638418, 2017). "However, deficiency of SOCS2 was reported to enhance Th2 differentiation in a murine model of allergy and asthma, in which STAT6 and STAT5 were activated, whereas STAT3, which is crucial for Th17 polarization was not." (PMID 31949423, 2019).
myocardial infarction (100 papers, 2011 to 2026). Gross necrosis of the myocardium, as a result of interruption of the blood supply to the area, as in coronary thrombosis. "In fact, one-week of treatment with dapagliflozin and empagliflozin before induction of myocardial infarction in mice reduced infarct size, and STAT3 activation was causally involved." (PMID 37620559, 2023). "Another study using cardiac-specific STAT3 knockout mice demonstrated that myocardial infarction increased myocardial fibrosis associated with the upregulation of fibrosis-related genes and enhanced cardiomyocyte hypertrophy." (PMID 32178385, 2020). "In contrast, enhanced heart-specific STAT3 activity led to increased inflammation upon myocardial infarction, underlining the importance of a correct control of STAT3 activation." (PMID 23460527, 2013). "An experimental study in pregnant mice and rats convincingly demonstrated, using in vivo and ex vivo models of acute myocardial infarction, that Intralipid significantly limited infarct size via the activation of STAT3." (PMID 38864969, 2025). "NOTCH1 signaling influences DLBCL development and myocardial infarction severity through the EZH2/STAT3 pathway, leading to increased heart fibrosis." (PMID 39951437, 2025). "Conversely, it promotes cardiomyocyte proliferation via the JNK/STAT3 pathway, aiding cardiac regeneration and repair after myocardial infarction." (PMID 40455761, 2025). "MT reduced myocardial infarction size by activating the JAK2/STAT3 pathway and upregulating HSP70 expression." (PMID 39041001, 2024). "Conversely, conditional deletion of STAT3 in cardiomyocytes exacerbates cardiac remodeling during the subacute phase of myocardial infarction or under chronic β-adrenergic stimulation." (PMID 38495094, 2024). "Inhibiting JAK2/STAT3 phosphorylation reduces malignant ventricular arrhythmias post-myocardial infarction by attenuating ventricular remodeling." (PMID 38495094, 2024). "Following myocardial infarction, the expression of STAT3 mRNA is reduced by miR-17-5p and miR-124, which leads to the deterioration of autophagy, inflammation, myocardial remodeling, and apoptosis." (PMID 38495094, 2024). "Previous research demonstrated that cardiomyocyte apoptosis caused by acute myocardial infarction resulted in a decrease in the bcl-2/bax ratio and expression of p-JAK2 and p-STAT3, while the expression of p-JAK2 and p-STAT3 protein increased significantly." (PMID 37567042, 2023). "The therapeutic roles of STAT3 in heart disease have been reported in various studies demonstrating that STAT3 is cardioprotective in pathological conditions such as myocardial infarction, ischemia/reperfusion and doxorubicin-induced dysfunction." (PMID 37019881, 2023). "Due to myocardial I/R, STAT3 upregulates the expression of Bcl-2, Bcl-xl, and other genes, which have been shown to reduce cell death and lessen adverse cardiac remodeling after myocardial infarction." (PMID 36969839, 2023). "The authors of another study concluded, that IL-10 inhibits inflammation and attenuates left ventricular remodeling after myocardial infarction via activation of STAT3 and suppression of HuR." (PMID 36209229, 2022). "IL-10 has been reported to increase the expression of intracellular galectin-3 through the activation of STAT3 in macrophages, which is essential for osteopontin-producing reparative macrophage polarization after myocardial infarction." (PMID 34987647, 2022). "One of these pathways has been described using preconditioning cells in the treatment of myocardial infarction, where miR-21 is a regulator of STAT3 signaling improving cardiac function parameters." (PMID 35625854, 2022). "In myocardial infarction, STAT3 is a stress protein of myocardial injury, and unrestricted activation of STAT3 is detrimental." (PMID 36670950, 2022).
myocardial infarction (continued). "It was concluded that Annexin A1 upregulation inhibits neutrophil infiltration and MPO activity likely via the activation of STAT3 signaling pathway in the rat model of myocardial infarction." (PMID 34943928, 2021). "In particular, in STAT3 null mice, reduced capillary density was detected compared to control mice after myocardial infarction, suggesting that cardiac specific ablation of the STAT3 gene leads to severe hypertrophy without coordination with capillary growth." (PMID 34642818, 2021). "In a mouse myocardial infarction model, STAT3 inhibition contributed to the reduction in ECM synthesis and protection of cardiac remodeling." (PMID 34056872, 2021). "Overall, STAT3 downregulation by hypertrophic pathological conditions can exacerbates IRI, and STAT3 intrinsic activity is required for the prevention of maladaptive cardiac remodeling in the subacute phase of myocardial infarction." (PMID 34642818, 2021). "In rats with myocardial infarction, SGLT2i attenuate myocardial fibrosis by activating the signal transducer and activator of transcription 3 (STAT3) pathway and reducing the release of superoxide and nitrotyrosine." (PMID 33827579, 2021). "Following I/R, IPC substantially reduced myocardial infarct size and significantly enhanced STAT3 phosphorylation in SOCS3-CKO mice compared to in WT mice." (PMID 34292971, 2021). "Of relevance, Stat3 phosphorylation levels are increased in myocardial infarction-induced cardiac fibrosis and shRNA-mediated knockdown of its putative mediator EphrinB2 reduced the extent of cardiac fibrosis and improved LV systolic function." (PMID 34445757, 2021). "High levels of intracellular galectin-3 expression are essential for the transcriptional activation of osteopontin [OPN; also known as secreted phosphoprotein 1 (Spp1)] in STAT3-mediated macrophage M2 polarization after myocardial infarction." (PMID 34307396, 2021). "lncRNA myocardial infarction associated transcript (MIAT) has a protective effect against the ox-LDL-induced apoptosis through inhibiting miR-181b and signal transducer and activator of transcription 3 (STAT3)." (PMID 34552965, 2021). "Krishnamurthy P, Rajasingh J, Lambers E, Qin G, Losordo DW, Kishore R. IL-10 inhibits inflammation and attenuates left ventricular remodeling after myocardial infarction via activation of STAT3 and suppression of HuR." (PMID 34133599, 2021). "As periostin delivery promotes myocyte proliferation and reduces injury size and fibrosis in myocardial infarction model rats, IL-13 presumably facilitates STAT3 and periostin induction for heart regeneration." (PMID 32178385, 2020). "Similar to the role of STAT3 in myocardial infarction, STAT3 is protective against ischemia/reperfusion injury by decreasing oxidative stress, apoptosis, and mitochondrial dysfunction, and by increasing angiogenesis." (PMID 32178385, 2020). "Overall, STAT3 plays pivotal roles in regulating the cardiac response during myocardial infarction, partly through regulating inflammation." (PMID 31709266, 2019). "Rapamycin reduces myocardial infarction in the diabetic mice heart via inhibiting mTOR thus activating the Janus kinase 2 (JAK2) /signal transducer and activator of transcription 3 (STAT3) signaling pathway." (PMID 30705773, 2019). "Rosuvastatin administered on the day before in vivo myocardial infarction (8 mg/kg single dose), and thereafter at 4 mg/kg orally for five weeks, enhanced p-STAT3/t-STAT3 in the peri-infarct area." (PMID 30424579, 2018). "Under conditions such as myocardial infarction (MI) and hypoxia, anti-inflammatory cytokines also promote angiogenesis via the STAT3 signaling pathway." (PMID 28978186, 2017). "Since we observed that EMPA did not alter the mitochondrial susceptibility to permeability transition, we concluded that the effect of EMPA in reducing myocardial infarction is STAT3 dependent." (PMID 29311992, 2017).